BRCA2 (BRCA2 DNA repair associated)
Diseases named in the same sentence as BRCA2 in open-access papers (continued):
Sharing a sentence is not in itself a finding about the gene and the disease.
breast cancer (continued). "Consistent with prior studies, a sample was classified as HRD for training purposes (i.e., ground truth) if it had an HRD score of at least 42 for breast cancer or 63 for ovarian cancer or if it harbored pathogenic germline variants, somatic mutations, or promoter methylation in BRCA1 or BRCA2." (PMID 40327608, 2025). "We found a coordinated behavior between BRCA1 and BRCA2 in breast cancer and observed BRCA1’s crypt-restricted expression in normal colorectal tissue, which may underlie its well-known tissue specificity." (PMID 41373491, 2025). "Data from one study show a protective role of breastfeeding against BRCA1-mutated breast cancer, but there is no protection for those with BRCA2 mutations." (PMID 41002733, 2025). "Additionally, germline mutations in the tumour suppressor genes breast cancer susceptibility genes 1 and 2 (BRCA1 and BRCA2) increase the risk of breast, ovarian, and related cancers." (PMID 40429877, 2025). "Female carriers of pathogenic variants in BRCA1 or BRCA2—both high-penetrance genes associated with hereditary breast and ovarian cancer (HBOC)—face a lifetime risk of 50%‐80% for breast cancer, a 60% risk for contralateral breast cancer, and up to 40% for ovarian cancer." (PMID 40471748, 2025). "Deficiencies in the DNA damage repair pathway related genes constitute an important factor in the development of breast cancer, with approximately 10% of breast cancer cases being caused by mutations in HR genes, such as BRCA1, BRCA2, PALB2, BRIP1, BARD1, and RAD51C." (PMID 40830526, 2025). "RTx-303 was administeredat 60 mg/kg (po, bid) in combination with 0.12 mg/kg (po, qd) talazoparibfor 42 days in female BALB/c mice inoculated with different BRCA2 mutant breast cancer PDX model (BR-05–0568).The combination treatment resulted in complete elimination of alltumors (left)." (PMID 41124685, 2025). "It should be noted that, presently, most of the reported clinically relevant breast cancer and Fanconi anemia genetic variants are located in BRCA2-DBD and not in PBD." (PMID 40232841, 2025). "Breast cancer is the most common cancer in Japanese women, and approximately 10% of these cancers are thought to be hereditary, with 4%–5% (about half of hereditary breast cancers) reported to be caused by BRCA1 or BRCA2 variants." (PMID 39831988, 2025). "•Factors impacting breast cancer prognosis include patient age, overall health, tumor stage, tumor size, lymph node involvement, histologic grade, and the presence of certain gene mutations (e.g., BRCA1 and BRCA2)." (PMID 40831739, 2025). "Epigenetic silencing of BRCA2/RAD51C drives ~30% HRD in male breast cancer." (PMID 40864792, 2025). "This may be due to the fact that common biomarkers for breast cancer, such as BRCA1 and BRCA2, have been linked to liver carcinoma as well." (PMID 40004168, 2025). "In contrast, for BRCA2-mut breast cancer, B3GNT7, CTSV, and GSDMC were the most significant." (PMID 40647506, 2025). "Because APE1 loss modulates sensitivity to replication stress-inducing agents like cisplatin rather than hormonal therapies, its impact on survival may be less pronounced in BRCA2 mutant breast cancer settings." (PMID 41162355, 2025). "Additionally, three candidate genes are associated with Breast cancer (DLL3, BRCA2, WNT2B), the mTOR signaling pathway (WNT2B, TELO2, TNFRSF1A), and Pathways in cancer (DLL3, BRCA2, WNT2B)." (PMID 40919429, 2025). "Hispanic women with breast cancer were 2.58 times as likely as non-Hispanic women to carry a P/LP germline BRCA1 mutation than BRCA2 mutation." (PMID 40952741, 2025).
breast cancer (continued). "We also examined BRCA2-mutant breast cancer cases using the METABRIC dataset." (PMID 41162355, 2025). "Thus, the prevalence of BRCA1 and BRCA2 VUS carriers among Brunei breast cancer patients was 8.3% and 25.8%, respectively." (PMID 40531958, 2025). "Although the biological differences between BRCA1- and BRCA2-associated breast cancers have been extensively studied, there is a lack of studies investigating how different treatment regimens influence QoL outcomes in this population." (PMID 40422528, 2025). "Here, we searched for potential drivers based on germline DNA analysis from a cohort consisting of patients with early-onset breast cancer negative for BRCA1/BRCA2 mutations." (PMID 40261702, 2025). "Concerning our two breast cancer patients with a proven BRCA2 methylation in the cancer cells, the use of PARP inhibitors may very well have been an option for the first patient in the metastatic setting." (PMID 39392573, 2025). "Genetic Studies conducted among women with breast cancer in countries such as Ghana, Nigeria, Uganda, Cameroon, and South Africa have found that most breast cancer cases are associated with mutations of the tumor-suppressing genes - BRCA1 and BRCA2." (PMID 40313245, 2025). "Furthermore, BRCA2 mutation/deletion is far more common in prostate cancer than BRCA1 loss of function, whereas in breast cancer, the relative frequencies on BRCA1 versus BRCA2 mutation are nearly equal." (PMID 40460119, 2025). "Another example is the phase III OlympiA trial, which included patients with HER2-negative early breast cancer with high-risk clinicopathological features and germline BRCA1 or BRCA2 pathogenic mutations who had received local treatment and neoadjuvant or adjuvant chemotherapy." (PMID 41333222, 2025). "The recommended surveillance is based on current UKCGG guidelines, including an anticipated change in guidance, implemented in April 2025, recommending that all individuals with a GPV in BRCA1/BRCA2/PALB2 are eligible for enhanced breast cancer surveillance from the age of 25 years." (PMID 41159931, 2025). "In this global study of young BRCA carriers with breast cancer, distinct patient, tumor, and treatment characteristics and a different pattern and risk of survival events over time were observed between patients carrying germline BRCA1 and BRCA2 PVs." (PMID 39993249, 2025). "In the development of breast cancer and ovarian cancer, lifestyle and environmental factors seem to play a statistically significant role in the presence of genetic predisposition associated with BRCA1 and BRCA2 gene mutations." (PMID 41092066, 2025). "Brunei BRCA2 carriers were more likely to have a positive family history of breast and/or ovarian cancers and have more than one family members in the first-degree relatives diagnosed with breast cancer." (PMID 40531958, 2025). "The overall prevalence of the studied BRCA1/2 variants in the unselected breast cancer cohort was 0.9% (21/2338, of which 7 BRCA1 and 14 BRCA2), which was significantly higher compared to controls (odds ratio [OR] 6.7, 95% confidence interval [CI] 2.24–19.70, p < 0.001)." (PMID 40009290, 2025). "Similarly, extensive investigations in breast cancer have demonstrated that alterations within BRCA1 and BRCA2 not only modulate cancer susceptibility but also significantly influence survival trajectories." (PMID 40833230, 2025). "The highest risk of breast cancer is determined for carriers of BRCA1 and BRCA2 mutations." (PMID 40724954, 2025).
breast cancer (continued). "In contrast, the CARRIERS (Cancer Risk Estimates Related to Susceptibility) study, which included individuals both with and without a strong family history of breast or ovarian cancer, reported breast cancer risk estimates of less than 50% by age 70 for carriers of P/LP variants in BRCA1 and BRCA2." (PMID 39858629, 2025). "Hispanic women with breast cancer were 2.58 times as likely as non-Hispanic women to carry a P/LP germline variant in BRCA1 than BRCA2 variants (odds ratio [OR], 2.58 [95% CI, 1.16-5.88]; P = .02)." (PMID 40952741, 2025). "More common than false negative test results are misapprehensions that a negative BRCA1 or BRCA2 test result in a woman at risk of familial breast and ovarian cancer means the patient will not develop a breast cancer." (PMID 40473778, 2025). "It is appropriate that the recently released American Society of Clinical Oncology/Surgical Society of Oncology genetic testing guidelines endorse germline testing for BRCA1 and BRCA2 in all newly diagnosed women with breast cancer who are younger than age of 65 years." (PMID 40952741, 2025). "Expanding access to genetic testing and availability of validated breast cancer (BC) risk prediction models are increasingly identifying women at elevated BC risk who do not carry high-penetrance BRCA1/BRCA2/PALB2 pathogenic variants." (PMID 40705362, 2025). "BRCA2 was associated with several genes that influence the inhibition of HDR and mechanisms that stimulate cell proliferation, mitotic abnormalities, and genomic instability in breast cancer cells." (PMID 40278313, 2025). "Furthermore, a significant interaction effect between BRCA2 PV status and PGS on cancer risk was observed for two cancers: female breast cancer (pinteraction < 0.001) and prostate cancer (pinteraction = 0.04)." (PMID 40462315, 2025). "While the association between BRCA2 mutations and breast cancer has been well studied, few or no studies have investigated the associations between BRCA2 mutations and other malignancies present in our case." (PMID 39702187, 2024). "Hereditary breast cancer, also known as familial breast cancer (FBC), accounts for 15% of all breast cancer cases, with HBOC syndrome, which is associated with BRCA1 or BRCA2 mutations and significantly increases the risk of breast and ovarian cancer, especially before the age of 50." (PMID 38543119, 2024). "While BRCA1/2 PVs have an extensive influence on tumourigenesis by affecting the tumour microenvironment, the differences in epigenetics of hereditary and sporadic breast cancers also predispose hereditary BRCA1 PV carriers and, to a lesser extent, BRCA2 ones, to the development of cancer." (PMID 39682099, 2024). "A hypothetical BRCA‐3 gene has been suggested for families with a significant history of breast cancer but no identified mutations in BRCA‐1 or BRCA‐2." (PMID 38827026, 2024). "Considering breast cancer-associated mutations across a broader range of genes (BRCA1, BRCA2, PALB2, and the more moderate-risk genes, ATM and CHEK2), the average carrier risk is equivalent to the top 3% of the PRS distribution (see S1 File for definition of mutation carriers)." (PMID 39292644, 2024). "The cumulative incidence risk of breast cancer by age 80 is reported to be 72% for BRCA1 mutation carriers and 69% for BRCA2 mutation carriers, while the cumulative incidence risk of ovarian cancer is 44% for BRCA1 and 17% for BRCA2." (PMID 39174799, 2024). "Limited data also suggested a higher rate of brain metastases in breast cancer with BRCA2 mutation, independent of the tumor histologic subtype." (PMID 38365640, 2024).
breast cancer (continued). "Tumor suppressor genes BRCA1, BRCA2, PALB2, and RAD51C play crucial roles in homology-directed recombination DNA repair (HDR) activity, and mutations in these genes have been implicated in breast cancer." (PMID 39430403, 2024). "While BRCA1 and BRCA2 remain the most well-known high-penetrance genes, others, such as ATM, BARD1, CHEK2, PALB2, RAD51C, and RAD51D, are now recognized as conferring moderate to high risk for breast cancer." (PMID 39590369, 2024). "On the basis of mutated genes in cBioPortal database, which was targeted sequencing of 2509 primary breast tumors with 548 matched normal tissues, a total of 30 genes including BBC driver mutations BRCA1, BRCA2, CHEK2 and other high frequency mutations in breast cancer were represented." (PMID 38800414, 2024). "One study conducted in Argentina that included 155 women with breast cancer, ovarian cancer, and both, with an average age of 42 years (range: 28–81 years), showed a prevalence of 25.8% of BRCA1 and BRCA2 mutations among patients who met the criteria for hereditary ovarian cancer." (PMID 39338246, 2024). "In 2 out of 6 patients with P/LP CHEK2 or BRCA2 variants, family history included breast cancer, but none met the current guidelines for genetic testing." (PMID 38415346, 2024). "An alternative approach (strategy #2) could entail discontinuing the ascertainment of family history of breast cancer and instead refer all women with a pathogenic variant in BRCA1, BRCA2, PALB2, ATM, and CHEK2 or a PRS in the top 10%." (PMID 39669587, 2024). "The same study reported that BRCA2-associated BC had a low frequency of ERα-negative (23%), PR-negative (35%), and triple-negative cases (16%), similarly to sporadic breast cancer." (PMID 38892081, 2024). "Moreover, MLH1 expression was regulated directly by estrogen, shedding light into the hormone-responsive nature of many BRCA2 mutant breast cancers." (PMID 38557488, 2024). "BRCA1 mutations are predominantly associated with estrogen receptor-negative breast tumors, but BRCA2 mutations are not linked to any specific pathological subtype of breast cancer." (PMID 38255960, 2024). "Indeed, in a recent case report of a female patient carrying two heterozygous pathogenic variants in BRCA2 and ATM, breast cancer was diagnosed at 34 and pancreatic cancer at 48 years." (PMID 38929805, 2024). "In our study, we clearly showed a 1.8% mutation rate of high penetrance genes, with 1.4% from BRCA1 and 0.5% from BRCA2, concealed in non-high-risk breast cancer patients, who needed alternations in management during their ongoing healthcare." (PMID 39272924, 2024). "Interestingly, BRCA1-type breast cancer lines all clustered with the basal subtype, whereas BRCA2-type breast cancer lines represented a variety of subtypes." (PMID 39485057, 2024). "Additionally, there is need to investigate other tumour suppressor genes including BRCA2 in breast cancer cases." (PMID 38952531, 2024). "Due to the diversity of the samples, we were able to interrogate the data relative to several key breast cancer risk modifiers, such as age, parity and BRCA1 or BRCA2 germline mutations, enabling us to uncover cellular interactions and compositional changes associated with each factor." (PMID 38548988, 2024). "While BRCA1/BRCA2 mutation is associated with all breast cancers, TNBC exhibits a higher proportion with BRCA1/2 mutation (20% with a germline mutation) than other breast cancer subtypes." (PMID 39272915, 2024). "The risk of breast cancer was highest for women with a pathogenic variant in BRCA1 or BRCA2: hazard ratio (HR) of 16.2 (95% CI: 10.9-24.1, P = 2.6e−76) for BRCA1 and HR = 8.5 (CI: 5.8-12.5, P = 1.3e−39) for BRCA2." (PMID 39669587, 2024). "Normal human physiology includes both BRCA1 and BRCA2, which are breast cancer genes." (PMID 38241592, 2024).
breast cancer (continued). "The biological relevance of the detected kinases is evident from their high mutation frequency in breast cancer, which is similar to other well-known non-kinase breast cancer markers such as BRCA2 and ESR1." (PMID 38784015, 2024). "Among the genes known to play a relevant role in mammary tumors, BRCA1 (BReast CAncer gene 1) and PALB2 (Partner And Localizer of BRCA2), two breast cancer susceptibility genes whose mutations result in familial cases of the disease, seem to be required for RARα signaling." (PMID 38360674, 2024). "A notable 5%–10% of newly diagnosed breast cancer cases are due to hereditary factors, mainly resulting from germline autosomal dominant mutations in the Breast Cancer Susceptibility Genes, BRCA1 and BRCA2." (PMID 39421188, 2024). "In breast cancer cells, the breast cancer susceptibility gene BRCA1 and BRCA2 genes are significant tumor suppressors for DNA double-strand breaks (DSBs) by homologous recombination (HR) and their mutation easily causes genetic instability and leads to the emergence of tumor cells." (PMID 38370471, 2024). "Women with a BRCA1 mutation and a breast cancer diagnosis have reduced time to progression and survival compared with BRCA2 mutation carriers and noncarriers of BRCA1/2 mutations." (PMID 38817906, 2024). "Approximately 5-10% of men with BRCA2 develop breast cancer, compared to 1-2% with BRCA1." (PMID 39314558, 2024). "Therefore, our team used second-generation sequencing to detect whole-exon susceptibility gene mutations and mutations in four breast cancer susceptibility genes (BRCA1, BRCA2, PALB2, and RECQL) in Chinese women." (PMID 38439896, 2024). "However, the number of breast cancer deaths in the BRCA2 cohort was small (n = 5) and the confidence limits were wide." (PMID 38421676, 2024). "Resveratrol, a phytochemical present in grapes, berries, and peanuts, has been discovered to regulate BRCA1 and BRCA2 genes in breast cancer cells and has inhibitory effect on cellular events associated with tumor initiation, promotion and progression, according to previous research." (PMID 38711004, 2024). "For this reason, acerola leaf extracts may be an important part of nutritional prevention for people at high risk of developing breast cancer, i.e., those with identified mutations in the BRCA1 and BRCA2 genes, or those with a family history of breast cancer." (PMID 38396766, 2024). "One explanation could be that the point of time at which RRBSO was performed was too late to attenuate breast cancer risk in this cohort, as the mean age of breast cancer onset is younger for BRCA1 than for BRCA2 pathogenic variant carriers." (PMID 38892081, 2024). "The co-expression of BRCA2 and ROCK2 in breast cancer suggest the joint effect in tumorigenesis, which may guide the effect enhancement of BRCA2 inhibitors on tumor cells." (PMID 39013885, 2024). "Even though other studies have also shown a benefit of BRRM for BRCA2 pathogenic variant carriers, a recent observational study did not confirm an increase in breast-cancer-specific survival for BRRM compared to surveillance in this subgroup." (PMID 38892081, 2024). "Conversely, PVs in the BRCA2 gene were predominantly found in luminal breast cancer cases." (PMID 38893140, 2024). "The most common genetic risk factor for breast cancer is a mutation in the BRCA1 and BRCA2 genes." (PMID 38920970, 2024). "Germline mutations related to breast cancer include BRCA1, BRCA2, CHECk2, ATM, PALB2, and PTEN." (PMID 39684874, 2024). "Breast cancer susceptibility genes BRCA1 and BRCA2 encode multifunctional proteins." (PMID 38711004, 2024). "Breast cancer is associated with genetic mutations in specific genes such as BRCA1 and BRCA2." (PMID 39096427, 2024). "Genetic testing is crucial in precision medicine for breast cancer, focusing on genes such as BRCA1 and BRCA2 to detect mutations that may raise breast cancer risk." (PMID 39590319, 2024).